FTO (FTO alpha-ketoglutarate dependent dioxygenase)
Diseases named in the same sentence as FTO in open-access papers (continued):
Sharing a sentence is not in itself a finding about the gene and the disease.
Stroke (9 papers, 2011 to 2024). Sudden impairment of blood flow to a part of the brain due to occlusion or rupture of an artery to the brain. "In our study, circSCMH1 overexpression attenuated Plpp3 deficiency by FTO-mediated m6A methylation, and promoted vascular repair after stroke." (PMID 36717587, 2023). "The genotypes GG+GT of rs17817449 at the FTO played a protective role in the risk of fatal stroke when the genotype TT was taken as a reference; in contrast, the genotype TT (major alleles) is a risk genotype in our study." (PMID 36530622, 2022). "However, the relationships between the MC4R and the FTO and the risk of a fatal stroke remain largely unknown." (PMID 36530622, 2022). "Our data demonstrate that circSCMH1 enhances vascular repair via FTO-regulated m6A methylation after stroke, providing insights into the mechanism of circSCMH1 in promoting stroke recovery." (PMID 36717587, 2023). "Collectively, these results indicate that specific expression of FTO in ECs improves motor function recovery after stroke." (PMID 36717587, 2023). "The level of FTO was significantly decreased in the peri-infarct cortex of the dMCAO and tMCAO stroke mice." (PMID 36717587, 2023). "Next, we examined the effect of endothelial-targeted FTO overexpression on motor function recovery after stroke." (PMID 36717587, 2023). "Here, the authors describe that a circular RNA interacts with FTO to promote vascular repair following stroke in mice and primates via mediating m6 A modification." (PMID 36717587, 2023). "Our findings indicated that circSCMH1 enhanced vascular repair via FTO-regulated m6A methylation, providing a previously overlooked mechanism of circSCMH1 in promoting stroke recovery." (PMID 36717587, 2023). "Together, these findings from human AIS patient and multiple murine stroke models support that stroke increases the m6A level in the peri-infarct cortex, which is plausible given the concomitant decrease in the FTO level in these samples." (PMID 36717587, 2023). "Nevertheless, we conducted a case-control study and a follow-up cohort study to provide evidence for the relationships between the FTO and stroke events, which is conducive to intervention in stroke occurrence earlier." (PMID 36530622, 2022). "We aimed to assess the associations between rs17817449 at the FTO and rs6567160 at the MC4R and the risk of stroke events in middle-aged and older Chinese people." (PMID 36530622, 2022). "A reasonable explanation for the different relationships between the FTO and stroke events should be a higher fto level in the brain, wherein the hypothalamus is located." (PMID 36530622, 2022). "We conducted a two-stage study to assess a series of associations between rs17817449 at the FTO and rs6567160 at the MC4R and the risk of stroke events." (PMID 36530622, 2022). "This indicates that FTO is decreased in the short term after stroke, which was confirmed by a recent report." (PMID 35747214, 2022). "The expression of major neuronally localized m6A demethylase FTO was downregulated, which presumably leads to decreased demethylation of m6A tagged RNAs in the post-stroke brain." (PMID 34150765, 2021). "In addition, a recent study has confirmed the neuroprotective effects of FTO in acute ischaemic injury, regulating white and grey matter damage and ameliorating cognitive decline and depressive-like behavior after stroke." (PMID 38384936, 2024). "CircSCMH1 promoted vascular repair after stroke through FTO-dependent m6A methylation." (PMID 36717587, 2023). "Therefore, it is indicated that specific expression of FTO in ECs contributes to vascular repair after stroke." (PMID 36717587, 2023). "Together, these results suggest that Plpp3 mRNA may be one of the targets of circSCMH1-mediated vascular repair after stroke by FTO." (PMID 36717587, 2023). "Like the Mannheim-Heidelberg stroke study in Germany, neither the FTO nor the MC4R was associated with LAA stroke in Han Chinese people." (PMID 36530622, 2022).
Stroke (continued). "The FTO decreased significantly after stroke compared with sham." (PMID 34395520, 2021). "In addition, a decrease in total m6A demethylase activity was reported in the study, indicating that FTO downregulation might be responsible for the decreased m6A demethylation in the post-stroke brain." (PMID 34150765, 2021). "Our study provided proof-of-concept evidence that circSCMH1 enhances vascular repair via FTO-regulated methylation, indicating that regulation of m6A methylation may be viewed as a potential therapeutic intervention for functional recovery after stroke in clinical applications." (PMID 36717587, 2023). "In a rat stroke model, the protein levels of demethylases FTO and ALKBH5 were changed, both FTO and ALKBH5 co-regulated m6A demethylation, which played a crucial role in cerebral ischemia/reperfusion (I/R) injury." (PMID 36246528, 2022). "The G allele of rs17817449 at the FTO, not rs6567160 at the MC4R, was associated with a decreased risk of fatal stroke occurrence; its functional role in stroke should be explored in relatively healthy middle-aged to older Chinese people." (PMID 36530622, 2022). "Rs17817449 at FTO, but not rs6567160 at the MC4R, was associated with the risk of fatal all strokes; the genetic loci should be a potential biomarker for stroke events, and its functional role in stroke needs to be explored in relatively healthy middle-aged to older Chinese." (PMID 36530622, 2022).
acute kidney injury (8 papers, 2022 to 2025). Sudden and sustained deterioration of the kidney function characterized by decreased glomerular filtration rate, increased serum creatinine or oliguria. "Elevated levels of total renal M6A were detected in cisplatin-induced acute kidney injury (cis-AKI) in mice, accompanied by alterations in METTL3, Mettl14, WTAP, FTO and AlKBH5." (PMID 37865763, 2023). "In addition, cisplatin-induced acute kidney injury in mice led to increased m6A levels and alterations in the expression of methyltransferase complexes, including METTL3, METTL14, FTO, and ALKBH541." (PMID 38297163, 2024). "A previous study demonstrated that overexpression of FTO could decrease the cisplatin-induced cell apoptosis in acute kidney injury, and in POI patients and mouse models, the expression level of FTO decreased significantly compared with that in the control groups." (PMID 35219326, 2022).
Cerebral ischemia (7 papers, 2022 to 2026). Restriction of arterial blood supply to the brain associated with insufficient oxygenation to support the metabolic requirements of the tissue. "Conversely, overexpression of FTO was shown to reverse m6A methylation and reduce the levels of neuronal apoptosis caused by cerebral ischemia." (PMID 36479246, 2022). "For instance, FTO inhibits oxidative stress by regulating Nrf2 expression in models of cerebral ischemia/reperfusion injury and modulates neuronal oxidative stress through ATF3 regulation in an m6A-dependent manner." (PMID 41602161, 2026). "FTO, a key demethylase involved in a variety of physiological processes, regulates mA demethylation to act importantly in cerebral ischemia-reperfusion injury." (PMID 35528516, 2022). "FTO is known to be involved in cerebral ischemia/reperfusion (I/R) injury." (PMID 38430221, 2024). "Also, FTO overexpression can inhibit neuronal ferroptosis by suppressing Src-like protein-tyrosine kinase (FYN) expression and dynamin-related protein 1 (Drp1) activity in cerebral ischemia/reperfusion (I/R) injury." (PMID 40712780, 2025).
endometriosis (7 papers, 2021 to 2025). The growth of functional endometrial tissue in anatomic sites outside the uterine body. "To determine the potential causal role of FTO-mediated m6A regulation in the development of endometriosis in vivo, we generated mice with uterine deletion of Fto (Ftod/d) by injecting Fto floxed C57BL/6 J mice (Ftof/f) with Cre-AVV through the uterus." (PMID 40000966, 2025). "Collectively, our findings underscore the critical role of FTO-mediated m6A regulation in the pathogenesis of endometriosis." (PMID 40000966, 2025). "Initially, we confirmed that the upregulation of the m6A eraser FTO in endometriosis led to a decrease in m6A levels in ectopic endometrial tissues." (PMID 40000966, 2025). "On the basis of the findings presented herein, we identify critical roles for FTO-mediated m6A modifications in the progression of endometriosis." (PMID 40000966, 2025). "Our findings revealed elevated levels of FTO in endometriosis, leading to a reduction in total m6A levels, thus indicating its substantial involvement in disease progression." (PMID 40000966, 2025). "In summary, we present compelling evidence supporting the upregulation of FTO and its functional relevance in endometriosis." (PMID 40000966, 2025). "In summary, these findings collectively suggest that the reduction in m6A mRNA methylation induced by FTO in endometriosis promotes the proliferation, migration, and invasion of endometrial stromal cells." (PMID 40000966, 2025). "Taken together, our findings suggest that FTO is the primary factor driving aberrant m6A modifications in endometriosis and is involved in its pathological processes." (PMID 40000966, 2025). "It was found that FTO-dependent m6A regulates the progression of endometriosis via the ATG5/PKM2 Axis." (PMID 37840133, 2023). "Three m6A regulators (HNRNPC, HNRNPA2B1, and FTO) were identified as being significantly overexpressed in endometriosis patients and were visualized utilizing a boxplot." (PMID 36672827, 2022). "Though the expression of HNRNPA2B1 and FTO showed opposite trends between bioinformatic analysis and validation, they demonstrated a significant expression change in the endometriosis group at the protein level." (PMID 36672827, 2022). "Furthermore, we demonstrated that the expression of FTO and its effect on m6A levels are regulated by estradiol (E2) and inflammatory factors, which are key drivers of endometriosis pathogenesis." (PMID 40000966, 2025). "Furthermore, we found that FTO-mediated m6A mRNA methylation regulates the RhoA pathway, thereby influencing cell migration and invasion in endometriosis." (PMID 40000966, 2025). "Recent studies have proved that m6A methylation transferase methyltransferase like 3 (METTL3) might play a key role in the development of endometriosis, while the other two m6A regulators, FTO and IGF2BP2, have also been reported to participate." (PMID 36672827, 2022). "Moreover, METTL3 expression in endometriosis was reduced in the ectopic vs. eutopic endometrium while FTO expression was elevated." (PMID 34906165, 2021). "We delved deeper into the relationship between FTO-mediated m6A modifications and their regulatory effects on the expression or translation of GEF-H1 in endometriosis." (PMID 40000966, 2025). "This research has demonstrated that some m6A regulators, such as METTL3, FTO, and IGF2BP2, participate in the process and development of endometriosis, while there are few studies on other m6A regulators." (PMID 36672827, 2022). "Another study has also identified three different m6A regulators (FTO, HNRNPC, and HNRNPA2B1) between the endometriosis and non-endometriosis groups." (PMID 37891533, 2023).
head and neck squamous cell carcinoma (7 papers, 2020 to 2025). A squamous cell carcinoma that arises from any of the following anatomic sites: lip and oral cavity, nasal cavity, paranasal sinuses, pharynx, larynx, and salivary glands. "In this study, we reported a positive feedback loop between SRSF6 and FTO, which helped head and neck squamous cell carcinoma (HNSC) cells resist ferroptosis and promoted HNSC progression." (PMID 40712780, 2025). "The lncRNA lnc-H2AFV-1 upregulates the expression of intraflagellar transport (IFT) 80 by regulating METTL3/14 and FTO in head and neck squamous cell carcinoma (HNSCC), thereby promoting cell growth." (PMID 38351139, 2024). "Lnc-H2AFV-1 was found to be upregulated in head and neck squamous cell carcinoma tissues, in which the expression of FTO was contrary to that of lnc-H2AFV-1." (PMID 37365581, 2023). "In HPV head and neck squamous cell carcinoma (HNSCC) models in humans and mice, genetic and pharmacological inhibition of FTO enhanced the efficiency of radiotherapy." (PMID 41369374, 2025).
ischemic stroke (7 papers, 2022 to 2025). A stroke disorder caused by obstruction of blood flow to the brain, due to thrombotic (local blood clot formation) or embolic (due to a blood clot or other material traveling from another site) event. "We evidenced that circSCMH1 interacted with FTO and increased its translocation into the nucleus, alleviating the increased level of m6A methylation after ischemic stroke." (PMID 36717587, 2023). "FTO-regulated vascular repair has been demonstrated in retinal and cardiac blood vessels, our findings pushes the frontier of basic understanding of the functional link between FTO and vascular repair in ischemic stroke." (PMID 36717587, 2023). "In response to ischemic stroke, neurons initiate a protective mechanism involving ubl carboxyl-terminal hydrolase 18 (USP18), which stabilizes the fat mass and obesity-associated protein (FTO) through deubiquitination, leading to increased FTO protein levels." (PMID 40705152, 2025). "One study investigated the role of trimethylamine N‐oxide in ischemic stroke and found it could promote the activation of the NLRP3 inflammasome in microglia through the FTO/IGF2BP2 pathway, thereby aggravating neurological injury in ischemic stroke." (PMID 39161158, 2024).
microcephaly (7 papers, 2013 to 2025). A congenital or acquired developmental disorder in which the circumference of the head is smaller than normal for the person's age and sex. "For example, in humans, a recessive loss‐of‐function mutation in FTO leads to postnatal growth retardation, microcephaly, facial dimorphism, functional brain deficits and death within 30 months of age." (PMID 40022434, 2025). "FTO-deficient mice exhibit growth retardation, microcephaly, severe psychomotor delay, functional brain deficits, and facial dysmorphism, reflecting the importance of FTO in nervous system development and differentiation." (PMID 38092760, 2023). "In Humans, a homozygous FTO mutation (R316Q) results in severe developmental defects including developmental delay, postnatal microcephaly, craniofacial dysmorphism and early lethality, suggesting that FTO plays a vital role during development." (PMID 24503721, 2014). "In humans, the FTO SNP that causes substitution R316Q and a loss of FTO activity gives an even more complex phenotype: postnatal growth retardation, microcephaly, severe psychomotor retardation, functional brain disorders, and a characteristic facial dysmorphism." (PMID 39329974, 2024).
psoriasis (7 papers, 2021 to 2024). An autoimmune condition characterized by red, well-delineated plaques with silvery scales that are usually on the extensor surfaces and scalp. "In our study, the A allele of rs1558902 in the FTO gene was associated with considerably greater BMI values, especially among type I psoriasis patients." (PMID 35806402, 2022). "Moreover, previous evidence has shown that polymorphisms in the FTO gene can affect the severity of psoriasis." (PMID 38436011, 2024). "One particular variant of the FTO gene, precisely the A allele of rs1558902, was found to be significantly associated with higher body mass index values, predominantly in individuals with type I psoriasis." (PMID 36980866, 2023).
viral infection (7 papers, 2021 to 2025). "For example, in HIV and Enterovirus infection, viral infection can increase writer (METTL3/14 (methyltransferase 3/14)) and decrease eraser (FTO (fat mass and obesity-associated protein) or ALKBH5 (alkB homolog 5)) levels and thus promote viral replication." (PMID 37325513, 2023). "Downregulation of one of the m6A erasers, FTO, by viral infection was also reported." (PMID 34502037, 2021). "Expression of this protein kinase, in the absence of virus infection, was sufficient to induce phosphorylation of FTO." (PMID 39791911, 2025). "Viral infection enhances the expression of METTL3/14 and DF1–3 at an early stage and decreases their expression at the late stage; however, the expression of ALKBH5 and FTO is consistently suppressed during infection." (PMID 37325513, 2023). "Next, we aimed to assess whether the expression of the UL13 protein kinase alone, in the absence of virus infection, is sufficient to trigger FTO phosphorylation." (PMID 39791911, 2025). "FTO might, therefore, be involved in regulating proteins within the canonical JAK-STAT pathway, as has been suggested before, or potentially in a non-canonical pathway that leads to ISG expression upon virus infection." (PMID 39791911, 2025).
developmental delay (6 papers, 2018 to 2023). "Diseases associated with FTO function include growth retardation, developmental delay, facial dysmorphism, coarse facies, and early death." (PMID 34063412, 2021). "FTO is a protein coding gene associated with growth retardation, developmental delay, and facial dysmorphism." (PMID 30631343, 2018).
morbid obesity (6 papers, 2009 to 2025). An excess of body weight, normally defined as an individual with a body mass index greater than 35 or a body weight greater than one hundred percent of ideal body weight. "In contrast, a duplication of the FTO gene was found to be associated with morbid obesity." (PMID 40630163, 2025). "However, a previous study in Mexican patients with morbid obesity, the rs9939609 “TA” genotype was significantly associated with higher FTO expression." (PMID 28464932, 2017). "Our model suggests that a search for human coding mutations in FTO may be informative and that inhibition of FTO activity is a possible target for the treatment of morbid obesity." (PMID 19680540, 2009). "Conversely, duplications of the FTO gene have been found to contribute to morbid obesity, further emphasizing its role in weight regulation and associated health risks." (PMID 40630163, 2025). "The observation that impaired FTO function results in a lean phenotype also suggests that inhibition of FTO may be of therapeutic interest in relation to morbid obesity." (PMID 19680540, 2009).
multiple myeloma (6 papers, 2022 to 2026). "Previous studies have demonstrated that in multiple myeloma, IDH2 enhances the expression of WNT7B and activates the WNT signaling pathway by targeting the m6A demethylase FTO, thereby promoting the occurrence and development of multiple myeloma." (PMID 39641872, 2024). "Expression levels of m6A are decreased in plasma cells of patients with multiple myeloma (MM) due to FTO-mediated demethylation, and inhibiting FTO suppresses MM cell proliferation, migration, and invasion." (PMID 38902779, 2024). "In multiple myeloma (MM), FTO has also a pro-metastatic role by targeting HSF1, enhancing HSF1 mRNA stability and translation." (PMID 37369946, 2023). "Transcriptome array analysis indicated that FTO was at a higher level in patients with multiple myeloma compared to healthy subjects." (PMID 35628623, 2022). "Importantly, FTO inhibition combined with bortezomib treatment synergistically inhibited myeloma bone tumor formation." (PMID 37369946, 2023). "According to the Arkansas myeloma cohort (GEO accession number GSE4581), the elevated expression of two m6A demethylases (ALKBH5 and FTO) was correlated with poor patient survival." (PMID 34759347, 2022).